RNU6-1288P (RNA, U6 small nuclear 1288, pseudogene)
Gene: Small nuclear RNA gene on chromosome 2 (14,274,622 to 14,274,725, reverse strand). Ensembl gene ENSG00000251859.
Homologues: Orthologues: chimpanzee U6 (99% identical), dog U6 (65% identical). Paralogues in human: RNU6-1060P (83% identical), RNU6-831P (83% identical), RNU6-1042P (82% identical), RNU6-520P (82% identical), RNU6-116P (81% identical), RNU6-1257P (81% identical), RNU6-15P (81% identical), RNU6-188P (81% identical), RNU6-21P (81% identical), RNU6-224P (81% identical), RNU6-657P (81% identical), RNU6-1024P (80% identical), and 1289 more.